CXCR5 (C-X-C motif chemokine receptor 5)
Diseases named in the same sentence as CXCR5 in open-access papers (continued):
Sharing a sentence is not in itself a finding about the gene and the disease.
tumor (continued). "Meanwhile, ST analyses corroborated conspicuous aggregations of B lineage cells (Naïve B, Memory B, GC B, and plasma cells), CD4_C8_CXCR5 and CD8_C8_CXCL13 T cells, and CXCL13+ CAFs (iCAF_C2_CXCL13) in the TLS regions of NPC tumours across Stereo-seq and Visium cohorts." (PMID 39231979, 2024). "Based on the Spearman correlation test, the expression of chemokine receptors CCR5 and CXCR5 on tumor significantly correlated with the RCB scores, indicating a poor response to chemotherapy, whereas the expression of CXCR5 in TILs correlated with a good response to NAC." (PMID 39001456, 2024). "Following activation by myeloid cells in tumour‐draining lymph nodes (dLNs), CD4+ and CD8+ T cells differentiate into various tumour‐infiltrating lymphocytes (TILs), encompassing T helper (Th1/Th2/Th17) cells, Tregs and Tfh cells (CD4+ CXCR5+ PD‐1high), among others." (PMID 38451000, 2024). "Additionally, CXCR5 and IL-7 co-expression enhanced CAR-T cell numbers, cytokine release, and survival in implanted tumor tissues compared to conventional CAR-T cells." (PMID 39450160, 2024). "Similarly, patients with a pCR were less likely to express CCR5, CCR7, CXCR4, and CXCR5 on tumors, and CXCR4 high expression (≥20%) on TILs in core biopsy tumor materials." (PMID 39001456, 2024). "Similarly, modification of the chemokine receptors CXCR1/CXCR2/CXCR5 to the surface of CAR-T cells can increase cellular transport within the tumor and anti-tumor efficacy." (PMID 38911868, 2024). "Response to ICI, but not to MAPKi, depends on the recruitment of CXCR5+ B cells into the tumor microenvironment and their productive tumor antigen presentation to follicular helper and cytotoxic, tumor reactive T cells." (PMID 37435085, 2023). "Additionally, responding patients had a lower tumor burden and displayed the expression of chemokine receptors (CCR7, CCR6, CXCR4, CXCR3, and CXCR5) on CD4+ T cells." (PMID 37174069, 2023). "Moreover, rare intratumoral CXCR5+PD1+ICOS+ TFH and CD4+CD25+CD127− Treg cells were more frequent in the tumor than the normal liver tissue." (PMID 35724271, 2022). "The results revealed that the proportion of CD4+CXCR5+CD69+ cells in peripheral blood CD4+ T cells was independent of tumor location in OS patients." (PMID 35081874, 2022). "CXCR5+CD8 T cells localize within blood circulation and tumor microenvironments of cancer patients." (PMID 36314014, 2022). "A sequence of events could be envisioned where tumor-reactive T-cells release CXCL134,23, attracting CXCR5 + LT + immune cells to the perivascular space initiating L1CAM-positive perivascular cell activation and maturation to FDCs." (PMID 35296668, 2022). "Further investigation revealed that tumor-infiltrating TFH cells produce CXCL13 to attract CXCR5+ CD8+ T cells and CXCR5+ B cells toward the germinal centers within the TLS, where both T cells and B cells are primed, reinforcing their cytotoxic capacity against cancer cells." (PMID 35053457, 2022). "In the context of malignancies, the CXCR5/CXCL13 axis induces proliferation, growth, invasion and migration of malignant cells and correlates with poorer prognosis, more metastasis, and larger tumor size in many cancers." (PMID 36221115, 2022). "Nevertheless, in hIgG1-G396R carriers, there were increased proportions of IgG+ plasma cells, CXCR5+ T follicular helper cells, CD6+ tumor-resident memory T cells, and decreased proportions of LAYN+ exhausted T cells, implying that the variant favors the formation of an antitumor microenvironment." (PMID 35133976, 2022). "The tumor cells also expressed one or more of CD10, CXCR5, ICOS, and PD1 wherever available." (PMID 35299754, 2022). "The transcriptional levels of 5 chemokines (CXCR5, CXCL12, CXCL13, CCL19, and CCL21) that have been reported to be involved in the formation of TLSs were also prominently elevated in both the tumor specimens from mIgG2c-G400R mice and hIgG1-G396R homozygous CRC patients." (PMID 35133976, 2022).
tumor (continued). "Although all these aspects in CXCR5+PD‐1+ CD8 T cells themselves could play a role, the low levels of tumor neo‐antigens combined with the poor antigen presentation by CLL cells could also play a role for the low response rates to PD‐1 ICB." (PMID 33098668, 2021). "The main finding of this study was that checkpoint blockade induced an influx of new T cell clones into the tumor tissue, which were identified as activated/exhausted tumor-specific CD8+ T cells (PD1+TIM3+CD39+CD103+); interestingly, the frequency of CXCR5+ Tfh was also increased after treatment." (PMID 33546283, 2021). "Moreover, in the NOD/SCID mice bearing A549-Luc-CXCL13 cells, CXCL13 recruits CXCR5+ CD68+ macrophages to the TME, where macrophages produce secreted phosphoprotein 1 (SPP1) to promote cell migration and tumor progression." (PMID 34947813, 2021). "As the presence of CXCR5+PD‐1+ CD8 T cells at the tumor site may be important in order to respond to PD‐1 ICB, we analyzed CLL LN biopsies for the presence of CXCR5+ CD8 T cells by histo‐cytometry analysis." (PMID 33098668, 2021). "Secondly, Tfh cells as part of the tumor microenvironment (TME) are concomitantly destroyed by CXCR5 CAR-T but not by CD19 CAR-T cells." (PMID 33431832, 2021). "It is well established that CXCR5 and its ligand CXCL13 play important roles in inflammation and immunity, and recent studies raised roles for this receptor in growth and metastasis of tumor." (PMID 34294713, 2021). "Residual JeKo-1 cells recovered from BM and spleen had a conserved expression of CXCR5 in both CAR-T cell groups, underlining that tumor recurrence was not a result of the selection for CXCR5 antigen loss variants." (PMID 33431832, 2021). "On one hand, CXCL13 attracts immunosuppressive cells to mediate immune suppression or evasion, leading to tumor progression, while on the other hand, the CXCL13/CXCR5 axis elicits tumoricidal immunity signaling to escape tumor immunosurveillance in some cancer types." (PMID 34947813, 2021). "CXCR5 has two transcripts, both localized on the cell membrane, and is expressed by follicular helper T cells (Tfh), circulating CD4+ T cells, B cells, CD68+ macrophages, and tumor cells." (PMID 34947813, 2021). "Therefore, we engineered an epidermal growth factor receptor (EGFR) CAR-T cell to express a second receptor CXCR5, to facilitate migration of CAR-T cells to the CXCL13-expressing NSCLC tumors, and to minimize EGFR-CAR-T possible off-tumor, on-target toxicity." (PMID 34553036, 2021). "Because CXCR5 is also expressed on Tfh cells, CXCR5 CAR-T cells offer an unprecedented opportunity to target the TME as well, a feature that was so far attributed to TCR-mediated effects on cross-presented tumor peptides in stromal cells." (PMID 33431832, 2021). "In particular, SLAMF6 and SLAMF1 expression in TAMs was increased by LFC = 2.1 and 3.5, both p.adj < 0.0001, and CXCL13 (LFC: 6.4, p.adj < 0.0001) and CXCR5 (LFC: 1.8, p.adj = 0.001) were highly upregulated in macrophages from the tumor compared to those from a normal lung." (PMID 33918618, 2021). "Collectively, the CXCR5 CAR-T cells exhibited no cross-reactivity or on-target/off-tumor effects against a wide range of human cell lines or primary cells." (PMID 33431832, 2021). "In addition to potentiating tumor-stromal cell crosstalk, the CXCL13/CXCR5 axis exerts intracellular signaling cascade reactions, which are conducive to malignant cell survival and resistance to apoptosis." (PMID 34947813, 2021). "In addition, CXCR4 and CXCR5 expression levels were remarkably different in tumor differentiation (CXCR4, P < 0.001; CXCR5, P < 0.001)." (PMID 32896997, 2020). "In addition, CXCR4 and CXCR5 expression were significantly different in tumor differentiation (CXCR4, P < 0.001; CXCR5, P < 0.001)." (PMID 32896997, 2020). "CXCR5 and CCR7 expression were found on the membrane and in the cytoplasm of tumor cells." (PMID 32896997, 2020).
tumor (continued). "Elevated expression levels of CXCR4, CXCR5 and CCR7 were found in tumor tissues (P < 0.001)." (PMID 32896997, 2020). "In contrast, for CXCR5+ tumors, antibody blockade of CXCL13 may be a useful strategy for preventing CXCL13-driven tumor growth and invasion." (PMID 33193299, 2020). "Further, the infiltrated CXCR5+CD4+ T cells was demonstrated to be significantly less in HCC tumor regions than that of non-tumor regions." (PMID 31507621, 2019). "Because tumour development is largely orchestrated by inflammation, MSCs exhibit upregulation of various chemokine receptors (CCR1, CXCR5 and CCR2) and adhesion molecules (ALCAM, P-selectin and integrins) to facilitate extensive tropism towards specific tumour sites." (PMID 31908585, 2019). "To assess the presence of CD8+CXCR5+ T cells within HCC tumors, we used flow cytometry to analyze the CD8+CXCR5+ T cell content in 20 healthy blood samples and 40 HCC specimens, each of which included blood, peritumoral liver, and tumor tissue samples the same patient." (PMID 31663864, 2019). "Thus, the blockade of PD-1–PD-L1 pathway is another feasible strategy to promote the CXCR5+CD8+ T cells function, as it has been proved in anti-tumor CD8+ T cells." (PMID 29085360, 2017). "Bindea and colleagues showed growth acceleration of MC38 isografts in Cxcr5−/− mice (CXCR5 is the receptor for CXCL13) compared to control, and rejection of tumour cells when recombinant CXCL13 was injected into the colonic submucosa of wild‐type mice before transplantation." (PMID 26115037, 2015). "We tested the expression of CXCR5 in 24 NSCLCs, and found that it was expressed by the tumor samples but was not significantly higher than in paired normal lung tissues (p=0.089)." (PMID 26565418, 2015). "Although the bulk frequency of circulating Tfh cells was not altered in HCC patients, the frequency of infiltrated CXCR5+CD45RA−CD4+ CD3+cells was higher in tumor than in para-tumor tissues, and Th1-like cells were the predominant phenotype." (PMID 26517519, 2015). "The proportion of infiltrated CXCR5+CD4+ T cells was significantly decreased in tumor regions compared with nontumor regions." (PMID 25689070, 2015). "We did not observe any distinct change in CXCR5 expression in AC cases with increased tumor stage and nodal metastasis." (PMID 25271023, 2014). "In this model, greatly elevated levels of CXCR5 are seen on the surface of tumor cells, and greatly elevated levels of murine, but not human, CXCL13 are seen in the serum and ascites of animals with tumors." (PMID 23936541, 2013). "Clearly, though, further studies will be needed to more precisely determine the role that CXCR5 and CXCL13 may be playing in tumor growth." (PMID 23936541, 2013). "Migration of metastatic tumor cells from the bloodstream into lymph nodes is thought to be facilitated by expression of the chemokine receptors CCR7, CXCR4 and, for B cell-derived tumors, CXCR5." (PMID 21672222, 2011). "We also did not observe any significant correlations between tumour RNA expression of CXCL13 or CXCR5 and clinical characteristics of individual patients (data not shown)." (PMID 18781150, 2008). "Accordingly, CXCR5 mRNA was consistently detectable using real-time PCR, but the tumour cells remained negative for surface expression of the protein even after the addition of activating cytokines." (PMID 18781150, 2008). "Similarly, CXCR5 was only observed to be upregulated in tumour non-naive B cells and Tfh T cells only in the AE but not in ME patients." (PMID 39915477, 2025). "The CXC motif chemokine receptor 5 (CXCR5) receptor, which guides cells to lymphoid tissues, might also assist CAR-T cells in navigating the complex stromal architecture of solid tumors, potentially leading to improved tumor invasion." (PMID 39450160, 2024).
tumor (continued). "However, during relapse in this model, they noted persistent CXCR5 antigen expression on the tumor cells, which meant that murine cytokines did not effectively support the long-term survival of human anti-CXCR5 CAR T cells." (PMID 39335157, 2024). "Intensive B cell marker staining and CD4+ TFH markers colocalized with PD-1T TILs, implying that CD8+PD-1T TILs might recruit CXCR5+ B cells and TFH cells into the tumor region and that B cells, as well as TFH cells, could reinforce the antitumor capacity of CD8+ T cells." (PMID 35053457, 2022). "In addition, we found that the expression levels of T-cell exhaustion-related genes including CD40, GRB2, MKI67, NFATC3, PRDM1, TCF7, and TGFB1 were significantly higher, while those of CXCR5 and TOX were significantly lower after tumor recurrence (all p < 0.05)." (PMID 34305618, 2021). "In addition, the CXCL13/CXCR5 axis also potentiates the crosstalk between tumor cells and lymphocytes or non-lymphocytes, shaping a complex TME." (PMID 34947813, 2021). "While only a minority of intratumoral stem-like cells express CXCR5, TCF-1+PD-1loCD8+ Tex also seem to localize as crude clusters in the TME, implying that there may be additional niche microenvironments within the tumor that support anti-tumor immunity." (PMID 34354714, 2021). "Furthermore, CXCR5+CD8+ T cells have been identified in tumours and tumour draining lymph nodes." (PMID 34326833, 2021). "Notably, similar antigen-specific IFNγ secretion was observed for both, the CXCR5 CAR-T as well as the CD19 CAR-T cells, although CD19 expression levels were on average 5–10-times higher than for CXCR5 on all tumor cell lines." (PMID 33431832, 2021). "To test our hypothesis, we first defined the area of TLS-like lesion (see “Methods” section) and then evaluated the abundance of TFH-like (CXCL13+CD4+), B (CXCR5+CD20+), and TRM-like (CD103+CD8+) cells within the TLS-like lesions of archival tumor tissue samples using multiplexed IF." (PMID 34663810, 2021). "Moreover, primary HCC-SN may provide a variety of tumor antigens, molecules, proteins, and microRNAs to mediate induction of CD8+CXCR5+ T cells and IL-21 production." (PMID 31663864, 2019). "In the present study, CXCL13 and CXCR5 were up-regulated in tumor tissues, especially in poorly differentiated tumors, suggesting that both CXCL13 and CXCR5 are correlated with HCC and their up- regulation were probably the results of integrated factors in worse tumor environment." (PMID 26517519, 2015). "In the case of primary intraocular lymphoma, tumor cells expressed CXCR5, and adjacent non-cancerous ocular cells expressed CXCL13, suggesting that these ocular cells might be directing tumor growth." (PMID 23936541, 2013). "In some of these cancers, tumor cells were shown to express both CXCL13 and CXCR5, suggesting a possibility for autocrine interactions, or CXCL13 was shown to be expressed in tissue surrounding tumors, raising the possibility that it could be directing the metastasis of tumor cells." (PMID 21490903, 2010). "Importantly, we did not observe significant numbers of tumour-infiltrating leukocytes expressing CXCL13 or CXCR5." (PMID 18781150, 2008). "Besides, no direct relationship of CD4 + CXCR5 protein expression with patients’ age, gender, tumor location, tumor diameter, degree of differentiation, TNM stage, presence/absence of signet-ring cells, and presence/absence of neural and vascular invasion (all P > 0.05)." (PMID 36859111, 2023). "The lesser expression of “poised” CXCR5+ B cells in ever smokers, suggests that with increasing genomic perturbations and evolutionary dynamics in smokers, the ability to recruit effector subsets, activate anti-cancer responses and form TLS may well be lost as a result of enhanced tumor escape." (PMID 37398676, 2023).
tumor (continued). "The emergence of these AITL‐like tumours in Trp53ER/ER;Vav1ΔC/ΔC mice requires long latency times, since we could not detect any significant alteration in the overall numbers of T cells and PD1+ CXCR5+ TFH populations in 2‐ and 6‐month‐old Trp53ER/ER;Vav1ΔC/ΔC mice." (PMID 35895495, 2022). "However, since tumor cells were negative for the Tfh chemokine receptor CXCR5, a definitive Tfh origin could not be concluded." (PMID 35510955, 2022). "Therefore, while CXCL13 in the tumour microenvironment might indicate B‐cell infiltration, tumour CXCR5 expression (rather than the TLS) could have a pro‐tumourigenic effect." (PMID 35218154, 2022). "We examined chemokine receptor expression of IgG+plasma cells in obese tumor samples and non-obese tumor samples, including CXCR3, CXCR4 and CXCR5, and found that IgG+plasma cells in obese CRC highly expressed CXCR4." (PMID 38311726, 2024). "Peripheral CXCR5-negative Tfh-like cells and Tfh that have migrated into the tumor are potent CXCL13 producers, attracting more B cells and CXCR5+ T cells to the TME." (PMID 36836910, 2023). "When the tumor cell has no endogenous CXCR5 expression, CXCL13 secretion in the tumor microenvironment can chemoattract CXCR5+ immune cells and trigger antigen-specific antitumor immunity." (PMID 35693216, 2021). "The anti-CXCR5 CAR endows T cells with high avidity, necessary for anti-tumor efficacy in vitro and in vivo without conferring unintended reactivity against various non-hematopoetic cell types." (PMID 33431832, 2021). "Administration of anti-murine CXCR5 CAR-T cells in syngeneic mice specifically depletes endogenous and malignant B and Tfh cells without unexpected on-target/off-tumor effects." (PMID 33431832, 2021). "By contrast, cell surface levels of other chemokine receptors, including CXCR5, CCR7 and CCR5, were not altered in vitro, or moderately increased in vivo after infiltrating tumours (Fig EV3C)." (PMID 31803974, 2020). "Culture supernatant from primary HCC tumor (HCC-SN) cells, but not from normal liver cells, showed a great ability to induce chemotaxis in CD8+CXCR5+ cells from healthy blood." (PMID 31663864, 2019). "CXCL13 is the ligand for CXCR5, and serum and ascites levels of murine, but not human, CXCL13 showed a striking elevation in tumor-bearing mice, with levels as high as 200,000 pg/ml in ascites, as measured by ELISA." (PMID 23936541, 2013). "The high levels of CXCR5 and murine CXCL13 that are seen in the 2F7 model thus raises the possibility, although does not prove, that murine CXCL13 (possibly produced by tumor-infiltrating cells) acts to promote tumor growth." (PMID 23936541, 2013). "Importantly, therapeutic modalities targeting CXCL13-CXCR5 signaling in the tumor microenvironment are currently being explored, although no small molecule pharmacological inhibitors directly targeting CXCL13 or CXCR5 have been yet developed." (PMID 36217194, 2022). "Regardless of whether blood or tumor was assessed, the majority of CD8+ T cells were CXCR5-, though a clear CD8+CXCR5+ T cell population was detected." (PMID 31663864, 2019).